PREP (prolyl endopeptidase)
Description:
Cleaves peptide bonds on the C-terminal side of prolyl residues within peptides that are up to approximately 30 amino acids long.
Synonyms: PE; PEP
Tractability: Small molecule: a structure with a bound ligand is known; a high-quality ligand is known; it belongs to a druggable protein family. Antibody: its Gene Ontology location is reachable by antibodies, with medium confidence. PROTAC: ubiquitination databases record sites on it; its protein half-life has been measured; a small molecule that binds it is known.
Target class: Protease; Serine protease SC clan; Enzyme; Serine protease; Serine protease S9A subfamily
Chemical probes: CHEMBL2159748
Gene: Protein-coding gene on chromosome 6 (105,273,218 to 105,454,062, reverse strand). Ensembl gene ENSG00000085377.
Subcellular location: Cytoplasm
Subcellular location (Human Protein Atlas): Cytosol
Gene Ontology:
Molecular function: protein binding; oligopeptidase activity; serine-type endopeptidase activity; serine-type peptidase activity; metallocarboxypeptidase activity; peptidase activity
Biological process: proteolysis; angiotensin maturation
Cellular component: cytosol; membrane; cytoplasm; extracellular region; nucleus
Genetic constraint (gnomAD): Loss-of-function variants: 23 observed, 82.59 expected, observed/expected ratio (o/e) 0.28, 90% interval 0.2 to 0.4. The upper end of that interval is the gene's LOEUF score, 0.4, which puts it in group 1 of 6, group 1 being the genes least tolerant of losing a copy. Missense variants: 676 observed, 893.78 expected, observed/expected ratio (o/e) 0.76, 90% interval 0.71 to 0.81. Synonymous variants: 325 observed, 333.83 expected, observed/expected ratio (o/e) 0.97, 90% interval 0.89 to 1.07.
Homologues: Orthologues: chimpanzee PREP (99% identical), macaque PREP (99% identical), guinea pig PREP (96% identical), mouse Prep (96% identical), rat Prep (95% identical), dog PREP (95% identical), pig PREP (94% identical), rabbit PREP (94% identical), tropical clawed frog prep (83% identical), zebrafish prep (76% identical), Drosophila melanogaster CG5355 (55% identical), Drosophila melanogaster CG2528 (52% identical). Paralogues in human: PREPL (17% identical).
Diseases named in the same sentence as PREP in open-access papers:
PREP is named in the same sentence as 75 diseases in open-access papers, as found by Europe PMC text mining. Sharing a sentence is not in itself a finding about the gene and the disease. The quoted sentences say what the papers report.
Alzheimer disease (10 papers, 2009 to 2025). A progressive, neurodegenerative disease characterized by loss of function and death of nerve cells in several areas of the brain leading to loss of cognitive function such as memory and language. "PREP has been associated with Alzheimer's disease and neurodegeneration, implicating PREP activity in memory." (PMID 19490636, 2009). "Peptides showing prolyl endopeptidase (PEP) inhibitory activity could be of interest as nootropic ingredients in functional foods, as altered PEP levels are associated with neuropathological disorders and different types of dementia such as Alzheimer’s disease." (PMID 34829125, 2021). "Alterations in PREP activity have been reported in several neurodegenerative diseases, including Parkinson's and Alzheimer's diseases, but there are no reports about PREP in MSA." (PMID 34486218, 2021).
Parkinson disease (8 papers, 2011 to 2023). A progressive degenerative disorder of the central nervous system characterized by loss of dopamine producing neurons in the substantia nigra and the presence of Lewy bodies in the substantia nigra and locus coeruleus. "Previous studies on PREP inhibition in Parkinson’s disease models found some evidence for the activation of autophagy." (PMID 37372009, 2023). "PREP inhibitors have been shown to have beneficial effects in Parkinson’s disease models by enhancing the clearance of aSyn aggregates and modulating striatal dopamine." (PMID 33579026, 2021). "Prolyl oligopeptidase (PREP) inhibition by small-molecule inhibitors can reduce alpha-synuclein (aSyn) aggregation, a key player in Parkinson’s disease pathology." (PMID 29367610, 2018). "In vivo, PREP inhibition reduces α-synuclein aggregates in a cellular and animal model for Parkinson’s disease." (PMID 26300881, 2015). "PREP and α-synuclein have been shown to co-localize in cell models of stress and in the substantia nigra of post-mortem Parkinson’s disease brain." (PMID 26300881, 2015). "PREP inhibitors have been shown to enhance the clearance of α-synuclein aggregates via autophagy activation and to reduce oxidative stress in cellular and animal models of Parkinson’s disease as well as in ARPE-19 cells with defunct proteasome activity." (PMID 37372009, 2023). "COS also mediate the inhibition of some important enzymes such as β-secratase, prolyl endopeptidase (PEP) and acetylcholinesterase (AChE) which are involved in neurodegenerative diseases such as Alzheimer's and Parkinson's." (PMID 24957872, 2011).
amnesia (4 papers, 2017 to 2024). Pathologic partial or complete loss of the ability to recall past experiences ( AMNESIA, RETROGRADE) or to form new memories ( AMNESIA, ANTEROGRADE). "AD patients had increased prolyl endopeptidase (PEP) activity related to their amnesia and OA demonstrated the highest PEP inhibitory activity among the unsaturated FAs." (PMID 32098382, 2020). "Additionally, prolyl endopeptidase (PEP) activity is associated with neurological diseases such as Alzheimer’s, amnesia, and schizophrenia." (PMID 39339395, 2024).
Cirrhosis (3 papers, 2015 to 2023). A chronic disorder of the liver in which liver tissue becomes scarred and is partially replaced by regenerative nodules and fibrotic tissue resulting in loss of liver function. "In this work, we hypothesized a decreased of circulating levels of PREP in cirrhosis and wanted to find out if the relationship was linked to systemic inflammation or/and neuroinflammation, as judged by the development of HE." (PMID 26420028, 2015). "Additionally, based on clinical evidence, circulatory PREP activity has been found to be strongly and negatively correlated with cirrhosis prognostic scores in cirrhotic patients." (PMID 37394591, 2023). "Furthermore, circulating PREP activity was observed substantially depressed in cirrhosis and in PCS rats with MHE." (PMID 26420028, 2015). "It is interesting to note that we found here a negative correlation between PREP activity and the severity of cirrhosis, as Child-Pugh and MELD scores." (PMID 26420028, 2015).
neuroblastoma (3 papers, 2015 to 2017). Neuroblastoma (NB) is the most common solid, extracranial childhood tumor. "Recent findings, using PREP overexpressing neuroblastoma cells, indicate that PREP is implicated in the regulation of PS-NCAM, most probably by modulating the proteases which normally degrade NCAM forms." (PMID 28261087, 2017). "Apparently, these cells secrete PREP upon activation with IFNγ and LPS and partly because of this, their supernatant is toxic to neuroblastoma SH-SY5Y cells, as shown through the use of PREP-specific inhibitors." (PMID 26300881, 2015). "In experiments on PREP overexpressed neuroblastoma cells, the data suggest that PREP has a role on secretion and clearance of α-synuclein deposits." (PMID 26420028, 2015). "Another study described physical interaction of PREP with GAPDH, and suggested that this would modulate GAPDH translocation to the nucleus during apoptosis in neuroblastoma cells." (PMID 28261087, 2017).
asthenospermia (2 papers, 2022 to 2025). "We have also demonstrated that PREP-/- mice presented reduced sperm motility, as well as the association of asthenospermia with impairment of PREP protein level and localization in human SPZ." (PMID 35563519, 2022).
Chagas disease (2 papers, 2018 to 2021). A parasitic infection caused by Trypanosoma cruzi. "All proteins in this family have been implicated in various clinical conditions; prolyl endopeptidase (PREP; OMIM 600400), oligopeptidase B (OpdB) (role in host cell invasion by Trypanosoma cruzi, Chagas disease), acylaminoacyl‐peptidase (APEH; OMIM 102645), and dipeptidase IV (DPPIV; OMIM 102720)." (PMID 34612606, 2021).
cognitive deficits (2 papers, 2022 to 2023). "As the loss of function mutations in human PreP are associated with neurological disorders, e.g., cognitive impairments/disability and cerebellar atrophy, our model should provide guidance for future investigation into how to boost PreP activity for better control of mitochondrial proteostasis." (PMID 35383169, 2022).
ischemia (2 papers, 2021 to 2025). A hypoperfusion of the BLOOD through an organ or tissue caused by a PATHOLOGIC CONSTRICTION or obstruction of its BLOOD VESSELS, or an absence of BLOOD CIRCULATION. "Prolyl endopeptidase (PREP) appears to be involved in inflammatory responses, so it could be a possible therapeutic target for counteracting ischemia injury." (PMID 40298805, 2025).
multiple sclerosis (2 papers, 2015). A progressive autoimmune disorder affecting the central nervous system resulting in demyelination. "Recently, it has been reported that circulating PREP activity is significantly decreased in patients of multiple sclerosis (MS)." (PMID 26420028, 2015). "Interestingly, PREP inhibition seems to aggravate symptoms in a mouse model of multiple sclerosis." (PMID 26300881, 2015). "However, we found no relation of PREP activity to the levels of α2M or effect of reducing agents, like DTT, on enzymatic activity in multiple sclerosis samples or in this study (data not shown)." (PMID 26420028, 2015).
steatosis (2 papers, 2016 to 2025). Increased lipid within the cytoplasm of cells. "The study identified five circulating proteins associated with the steatosis grade in the liver: Cathepsin O (CTSO), Cadherin 2 (CDH2), Leukocyte immunoglobulin-like receptor subfamily A member 5 (LILRA5), and Serpin B6 (SERPINB6); and Prolyl endopeptidase (FAP)." (PMID 39017916, 2025). "Five circulating proteins, including Cathepsin O (CTSO), Cadherin 2 (CDH2), and Prolyl endopeptidase (FAP), were identified as biomarkers for steatosis." (PMID 39017916, 2025).
synucleinopathies (2 papers, 2018 to 2021). "Our results suggest that PREP inhibition could be a possible disease‐modifying therapy that is applicable for several synucleinopathies." (PMID 34486218, 2021). "Taken together, although aSyn forms aggregates in the absence of PREP, our findings showed that PREP is important for aSyn-mediated toxicity and this further emphasizes the possibilities of PREP inhibitors as disease-modifying drugs for PD and other synucleinopathies." (PMID 29367610, 2018).
adenoma (1 paper, 2015). A neoplasm arising from the epithelium. "Previously, it was reported that the activity and expression of two other serine peptidases, fibroblast activation protein alpha (FAP) and prolyl endopeptidase (PEP), was higher in adenomas and in early stages of CRC respectively." (PMID 25790122, 2015).
anaemia (1 paper, 2017). "Amongst 1198 PReP-participants [69.0 ± 10.6 years, 25.3% female, New York Heart Association (NYHA) class 2.4 ± 0.5, LVEF 35.3 ± 7.2%], ID was found in 42.5% (previously unknown in all), and anaemia in 18.9% (previously known in 4.8%)." (PMID 28229219, 2017).
autoimmune disease (1 paper, 2021). A disorder resulting from loss of function or tissue destruction of an organ or multiple organs, arising from humoral or cellular immune responses of the individual to their own tissue constituents. "Prolyl endopeptidase (PREP) is a serine protease with enzymatic activity and the ability to cleave short proline-containing peptides (smaller than 3 kDa) involved in inflammatory response activation, neurodegenerative diseases development, and autoimmune diseases’ outcome." (PMID 34680471, 2021).
chronic lung disease (1 paper, 2021). According to the definitions of the American and British Thoracic Societies, including pulmonary functional tests, X-rays, and CT scans for items such as fibrosis, bronchiectasis, bullae, emphysema, nodular or lymphomatous abnormalities. "With LPS stimulation, airway epithelial cells release excessive EVs that are enriched with prolyl endopeptidase (PE), an extracellular protease critical to the regulation of inflammatory responses in various human chronic lung diseases." (PMID 33742451, 2021).
colitis (1 paper, 2020). Inflammation of the colon. "Overall, these data indicate that PREP deficiency accelerates the development of DSS-induced colitis in mice, which is likely attributed to the decreased level of AcSDKP." (PMID 32435194, 2020). "PREP deficient mice showed enhanced susceptibility to DSS-induced colitis and displayed more severe colon damage and more robust inflammatory reactions, suggesting that the decreased level of AcSDKP might partly explain the detrimental effects of PREP deficiency." (PMID 32435194, 2020). "To uncover the potential role of AcSDKP in the pathogenesis of colitis, we knocked out the gene of PREP to inhibit the generation of AcSDKP in mice." (PMID 32435194, 2020). "Next, PREP-KO male mice and WT male littermates were exposed to 2.5% DSS for 7 days to induce UC-like colitis." (PMID 32435194, 2020). "Of note, the AcSDKP level in the colon was not significantly affected due to DSS-induced colitis, in either PREP-KO mice or WT mice." (PMID 32435194, 2020). "Of note, no spontaneous colitis was observed in PREP-KO mice." (PMID 32435194, 2020).
colorectal cancer (1 paper, 2023). A primary or metastatic malignant neoplasm that affects the colon or rectum. "It has been reported that the activity of prolyl endopeptidase is associated with the prognosis of colorectal cancer." (PMID 37256127, 2023).
colorectal tumors (1 paper, 2021). "PREP is mainly found in the brain; however, significant PREP activities and protein levels have been measured in peripheral tissues, such as the liver and colorectal tumors." (PMID 34095107, 2021).
disc degeneration (1 paper, 2022). "In a mouse model of puncture-induced disc degeneration, the PREP-knockout (PREP-KO) group showed slight disc degeneration compared to that in the wild-type (WT) group." (PMID 35464773, 2022). "The in vivo knockout of PREP attenuates puncture-induced disc degeneration, indicating that PREP may have significant value in the treatment of IVDD." (PMID 35464773, 2022). "Our study confirmed that the increased expression of PREP during disc degeneration and changes in the expression of PREP in NP cells under oxidative stress may be related to the PI3K/AKT signaling pathway." (PMID 35464773, 2022).
fibrosis (1 paper, 2021). the formation of excess fibrous connective tissue in an organ or tissue in a reparative or reactive process. "Our results clearly showed that PREP inhibition reduced intestinal fibrosis in mice, demonstrating that KYP-2047 administration may contribute to preventing intestinal fibrosis and reducing ECM deposition following intestinal IRI." (PMID 34680471, 2021).
Hepatic steatosis (1 paper, 2021). Steatosis is a term used to denote lipid accumulation within hepatocytes. "We investigated the role of PREP disruption in the crosstalk between gut flora and hepatic steatosis or inflammation in mice with NAFLD." (PMID 34095107, 2021). "PREP disruption may target multiple hepatic mechanisms related to the liver, gut, and microbiota, displaying a dynamic role in hepatic steatosis and inflammation during NAFLD." (PMID 34095107, 2021).
Hypertension (1 paper, 2018). The presence of chronic increased pressure in the systemic arterial system. "The mechanism of FAM110A, PREP, ANKRD9, DCPS, WFDC12, TPTE, and LAMB2 genes on the occurrence and development of hypertension is not yet clear." (PMID 29379041, 2018).
leukemia (1 paper, 2022). A malignant (clonal) hematologic disorder, involving hematopoietic stem cells and characterized by the presence of primitive or atypical myeloid or lymphoid cells in the bone marrow and the blood. "A previous CRISPRi screen showed that PreP was essential for the robust cell proliferation of human K562 leukemia cells." (PMID 35383169, 2022).
Leydig cell tumor (1 paper, 2021). A sex cord-stromal tumor occurring in the testis and rarely in the ovary. "Herein, for the first time, the potential relationships between the cytoskeleton-associated proteins DAAM1 and PREP with different testicular disorders, such as classic seminoma (CS), Leydig cell tumor (LCT), and Sertoli cell-only syndrome (SOS), were evaluated." (PMID 34360857, 2021).
liver disease (1 paper, 2015). "In general, the greater the score in both Child-Pugh and MELD systems, the greater the severity of the liver disease, and the lower the circulating PREP activity level, according to our results." (PMID 26420028, 2015).
liver failure (1 paper, 2015). A liver disease characterized by the liver losing or has lost all of its function. "In this work, we studied the variation of PREP levels upon liver failure and correlated it with several inflammatory markers to conclude on the relation of PREP with systemic and/or neuroinflammation." (PMID 26420028, 2015).
liver fibrosis (1 paper, 2023). "Among the regulated downstream genes, the expression of genes encoding profibrotic cathepsin B and D was suppressed by PREP in macrophages, explaining the protective role of PREP against liver fibrosis." (PMID 37394591, 2023). "Our results indicate that PREP in macrophages functions as a transcriptional coregulator that finely tunes macrophage functions, and plays a protective role against liver fibrosis pathogenesis." (PMID 37394591, 2023). "In addition, global knockout of PREP is not as powerful as macrophage-specific knockout in validating the predominant role of macrophages in PREP/cathepsin axis-related aggravated liver fibrosis." (PMID 37394591, 2023).
lung diseases (1 paper, 2023). "In this context, recent scientific research has identified new molecules involved in angiogenesis and inflammation, such as the prolyl oligopeptidase (PREP), a proteolytic enzyme belonging to the serine protease family, linked to the pathology of many lung diseases such as pulmonary fibrosis." (PMID 37626373, 2023). "Our in vitro model allowed to understand whether PREP could represent a hypothetical target for the treatment of lung diseases." (PMID 37626373, 2023). "Furthermore, since PREP itself is also present in neutrophils, it plays a role in supporting neutrophilic inflammation, which links PREP to the pathology of many lung diseases such as IPF." (PMID 37626373, 2023).
NK/T cell lymphoma (1 paper, 2015). "The deletion of 6q21 has been identified as the common genetic aberration in NK/T cell lymphoma (20–43%), and the genes located in the region of 6q21, including POPDC3, PREP, PRDM1, ATG5, AIM1, HACE1, and FOXO3, were reasonably considered the affected candidates." (PMID 26221594, 2015).